OCLN (occludin)
Diseases named in the same sentence as OCLN in open-access papers (continued):
Sharing a sentence is not in itself a finding about the gene and the disease.
ovarian tumor (5 papers, 2013 to 2026). "Mechanistically, A20 induced occludin endocytosis and lysosomal degradation via its ovarian tumor (OTU) domain." (PMID 41904194, 2026). "This research was conducted to examine the expression of claudin-6, occludin and MMP-2 in 36 ovarian papillary serous carcinomas and 26 ovarian serous adenomas specimens, and investigate the relationship between their expression and clinical properties of the ovarian tumor patients." (PMID 24245968, 2013).
Parkinson disease (5 papers, 2020 to 2025). A progressive degenerative disorder of the central nervous system characterized by loss of dopamine producing neurons in the substantia nigra and the presence of Lewy bodies in the substantia nigra and locus coeruleus. "A similar trend has been observed in patients with early Parkinson’s disease, characterised by alterations of occludin and zonulin-1 expression in colonic tissues." (PMID 32429301, 2020). "In mouse models of Parkinson’s disease and brain injury, sodium butyrate increased occludin and zonula occludens-1 (ZO-1) expression in the hippocampus and frontal cortex, supporting BBB function, while supplementation with 2% butyrate in G93A mice restored gut integrity and extended lifespan." (PMID 41154611, 2025). "In a mouse model of Parkinson’s disease (PD), 6-shogaol counteracted the decreases of occludin and ZO-1 proteins and reduced the production of tumor necrosis factor-alpha (TNF-α) and IL-1β in the colon, thereby preventing inflammation-induced gastrointestinal dysfunction." (PMID 36355111, 2022). "In models of parkinsonism induction, sodium butyrate has been shown to inhibit the permeability of the BBB through the upregulation of occludin and ZO-1." (PMID 38025189, 2023).
allergic asthma (4 papers, 2021 to 2025). A asthma with a basis in a pathological type I hypersensitivity reaction. "In an HDM-induced allergic asthma mouse model, FF and mometasone furoate had positive effects on mucosal permeability and increased the mRNA expression of occludin and ZO-1." (PMID 41303221, 2025). "The tight-junction protein of lung tissues is closely related to the pathological state of allergic asthma, which is represented by the expression level of ZO-1, Claudin1, Claudin4, and Occludin." (PMID 33542675, 2021). "In a mouse model of allergic asthma, acute HDM exposure significantly increased TGFβ1 protein in the BAL fluid, decreased expression of CDH1 and occludin in the airway epithelium, and increased expression of VIM, αSMA and pro-collagen 1 in the mesenchyme." (PMID 36230980, 2022).
allergic rhinitis (4 papers, 2021 to 2023). Inflammation of the nasal mucous membranes caused by an IgE-mediated response to external allergens. "Patients suffering from house dust mite-induced allergic rhinitis showed an increased epithelial permeability and decreased occludin expression." (PMID 36354438, 2022). "Furthermore, mRNA and protein expression levels of claudin-1 and occludin were increased by EOM treatment in allergic rhinitis, indicating that EOM is effective in defending the nasal barrier." (PMID 36578435, 2022). "This study assessed the mRNA expression levels of various tight junctions, including occludin (OCLN), claudin-3 and −7 (CLDN3 and CLDN7), desmoglein 3 (DSG3), and thymic stromal lymphopoietin (TSLP) in 30 individuals with Allergic Rhinitis (AR) and 30 non-allergic controls." (PMID 37692890, 2023).
Anxiety (4 papers, 2022 to 2025). Intense feelings of nervousness, tension, or panic often arise in response to interpersonal stresses. "Thus, submucosal EGC–derived GSNO may contribute to intestinal barrier dysfunction in IBS-D by downregulating occludin and ZO-1 expressions and cause worsening of symptoms, including visceral hypersensitivity, anxiety, and diarrhea." (PMID 36105292, 2022). "Our study found that WLR01 treatment increased the expression levels of occludin and ZO-1 in mice, which is consistent with Lactobacillus plantus LZU-J-TSL6 being used as a probiotic to exert an indirect or direct anti-anxiety effect by protecting intestinal barrier integrity." (PMID 39339809, 2024). "EA may downregulate EGC-derived GSNO expressions, repair the intestinal barrier by upregulating ZO-1 and occludin, restore intestinal homeostasis, and eventually relieve IBS-D symptoms such as visceral hypersensitivity, anxiety, and diarrhea." (PMID 36105292, 2022). "ZSSF treatment dramatically reduced anxiety-like behaviors, exerted sedative–hypnotic effects, increased hippocampal 5-HT and 5-HTP, and enhanced intestinal barrier function through inhibiting colon ZO-1, Claudin-1, and Occludin expression and reducing TNF-α, IL-6, and IL-1β levels." (PMID 40077533, 2025).
Arthritis (4 papers, 2020 to 2025). Inflammation of a joint. "Similar results were found at mRNA expression level with downregulation of ZO-1 and occludin before the onset of arthritis, while the expression of ion and water channel-forming TJ proteins claudin-2 and -15 went up." (PMID 32332732, 2020). "Furthermore, expression of TJ proteins ZO-1 and occludin was decreased before the onset of arthritis in the small intestine and shortly after onset of arthritis in the colon." (PMID 32332732, 2020). "These experiments confirmed that SB alone mimicked key therapeutic effects of EMS, including the amelioration of arthritis, inhibition of pro-inflammatory cytokines (IL-6, TNF-α, and IL-17A), and crucially, the restoration of intestinal barrier integrity (ZO-1 and occludin)." (PMID 41309372, 2025). "Occludin and ZO-1 mRNA expressions were not different whatever the stage of arthritis." (PMID 37280714, 2023).
bacterial meningitis (4 papers, 2016 to 2022). Inflammation of the membranes surrounding the brain and spinal cord due to a bacterial infection. "Downregulation of NEAT1 effectively maintained BBB integrity and decreased BBB permeability in bacterial meningitis experimental models through upregulating miR-135a and downregulating HIF1α to increase the expression of ZO-1, occludin, and claudin-5." (PMID 35346266, 2022). "Interestingly, MMP8 has been shown to facilitate blood brain barrier (BBB) disruption and increased permeability in bacterial meningitis by mediating proteolytic cleavage of the tight junction protein occludin, and detachment of human brain microvascular endothelial cells." (PMID 27050077, 2016). "The enhanced VEGFA expression led to downregulation and altered distribution of tight junction proteins such as ZO-1, occludin, and claudin-5, which eventually increased BBB permeability in bacterial meningitis." (PMID 35346266, 2022). "In studies of bacterial meningitis, MMP 8 degrades occludin, an integral plasma-membrane protein present in the tight junctions that form the BBB." (PMID 30258397, 2018).
cerebral embolism (4 papers, 2011 to 2024). "Occludin tyrosine-phosphorylation was enhanced by the cerebral embolism, and this was associated with an increase in activity of the c-Src tyrosine kinase, and a decrease in the level of endothelial occludin." (PMID 32457645, 2020). "A decrease in occludin and ZO-1 expression in BECs after cerebral embolism has been reported and localization of occludin, ZO-1, and ZO-2 proteins was altered after hypoxia in vitro." (PMID 21349151, 2011).
chronic kidney disease (4 papers, 2019 to 2023). Impairment of the renal function secondary to chronic kidney damage persisting for three or more months. "In a colonic inflammation model induced by chronic kidney disease (CKD), the Nrf2 activator, dh404, restored the levels of epithelial tight junction proteins including ZO-1, occludin, and claudin-1." (PMID 31346356, 2019).
depression (4 papers, 2020 to 2024). "Zonulin and occludin levels also increased in line with the severity of the accompanying depression." (PMID 39109367, 2024). "Consistent with the previous literature, zonulin and occludin levels increased in line with the severity of depression in MDD accompanying OCD in the present research." (PMID 39109367, 2024). "CLDN5 mRNA was increased in the occipital cortex (P = 0.0505) and cerebellum (*P = 0.0284) in bipolar brains, while OCLN was significantly increased in the occipital cortex (*P = 0.0397) of depression brains." (PMID 33139732, 2020). "Analysis of tight junction transcripts revealed discordant results with significant increases in CLDN5, OCLN and mRNA in bipolar and depression brains samples." (PMID 33139732, 2020). "Compared to OCLN and ZO-1, CLDN-5 and VE-cad are proved to be more vulnerable to H2O2, whose OS-causing depression could be erased by FGFC1 at high concentration (100 μM)." (PMID 39195457, 2024). "We measured three tight cell junction proteins (JAM-A, claudin 5 and occludin), and additionally the ICAM-1/collagen IV ratio in the later-life depression and later-life control groups." (PMID 37700368, 2023).
epidermoid carcinoma (4 papers, 2014 to 2025). "In a mixed cohort of squamous cell carcinomas from 9 different sites of origin, low occludin expression was associated with absence of HPV infection (p = 0.0001)." (PMID 40173205, 2025). "Occludin positivity was most seen in adenocarcinomas (37.5-100%) and in neuroendocrine neoplasms (67.9-100%), slightly less frequently in squamous cell carcinomas (23.8-93%) and in malignant mesotheliomas (up to 48.1%) and only rarely in non-Hodgkin’s lymphomas (1-2%) and in most mesenchymal tumors." (PMID 40173205, 2025). "IGF-1 has been shown to increase transepithelial electrical resistance (a measure of barrier function) by regulating occludin and claudin-3 in submandibular gland cells, zona occludens (ZO)-1 in A431 human epidermoid carcinoma cells and claudin-1 in osteoblast cells." (PMID 24618563, 2014). "The positive control, obtained from the epidermoid carcinoma cell line (A431), demonstrated a strong expression of both claudin-1 and occludin in comparison to HT-29 cells indicating that HT-29 cells might have the low endogenous expression of tight junction proteins." (PMID 34646849, 2021).
Giardia infection (4 papers, 2013 to 2023). "This is the case in Giardia infections where the re-arrangement of ZO-1, α-actinin, occludin and F-actin has been reported in in vitro studies together with the increase in the permeability of epithelial cell monolayer." (PMID 29726306, 2018). "Consistent with previous studies that demonstrated tight junctional disruptions in giardiasis, we detected occludin cleavage in the jejunum of G. lamblia-infected mice during peak parasite colonization." (PMID 23991642, 2013). "We observed increased occludin cleavage in the jejunal mucosa on PI days 7 and 35 following Giardia infection." (PMID 23991642, 2013).
hematoma (4 papers, 2018 to 2025). A hematoma is a collection of blood from a vascular structure into an extravascular space. "Therefore, in the present study, hematoma volume was considered as a confounding factor for the association of serum occludin levels and PHE volume." (PMID 37721332, 2024). "MAT improved neurological performance, reduced hematoma volume and brain edema, and restored blood-brain barrier integrity through upregulation of tight junction proteins (ZO-1, Occludin, Claudin-4)." (PMID 41400019, 2025). "Pearson's correlations of baseline serum occludin level, baseline hematoma volume, and perihematomal edema volume." (PMID 37721332, 2024). "Moreover, PHE volume (r = 0.426, p < 0.001) was higher correlated with serum occludin level than hematoma volume (r = 0.230, p < 0.05)." (PMID 37721332, 2024). "Furthermore, the knockdown of Nr4a1 significantly increased the expression of p-NF-κB p65, IL-1β, TNF-α, and MMP-9 with a decrease of ZO-1, occludin, and Lama5 in the peri-hematoma tissue." (PMID 31660977, 2019). "Partial correlation analysis showed that a high baseline level of serum occludin showed a linear correlation with the PHE volume (r = 0.675; p < 0.001), after adjusting hematoma volumes." (PMID 37721332, 2024). "Hematoma size, hemispheric enlargement and degenerating neuron count were significantly lower in the Apo-MSC group than in the naïve MSC group (p = 0.004, 0.013 and 0.043, respectively), while the expression of occludin was higher (p = 0.024)." (PMID 30469327, 2018).
hyperlipidemia (4 papers, 2021 to 2024). "While pomegranate and pomegranate leaf, which are rich in EA, can relieve the decrease of ZO-1 and occludin caused by alcoholic liver disease or hyperlipidemia in the intestine of mice." (PMID 35436978, 2022). "The study on Sprague–Dawley rats with hyperlipidemia also confirmed that the expression of ZO-1 and occludin protein in the intestine decreased and the permeability of intestinal mucosa increased." (PMID 34880767, 2021).
injury (4 papers, 2018 to 2023). Damage inflicted on the body as the direct or indirect result of an external force, with or without disruption of structural continuity. "Moreover, administration of progesterone improved brain function through reducing BBB permeability and increasing occludin expression in rats with traumatic brain injury, and progesterone receptor antagonist directly inhibited these functions." (PMID 31182728, 2019). "Meanwhile, the supplementation of probiotic Lactobacillus rhamnosus GG (LGG) might improve intestinal integrity by inhibiting miR122a, which resulted in occludin restoration, and increasing mRNA expression of tight junction (TJ) proteins in mice with alcohol-induced liver injury." (PMID 36819034, 2023).
Intestinal inflammation (4 papers, 2021 to 2025). "Intestinal inflammation can lead to the destruction of colonic mucosal tight junctions, and the expression of ZO-1 and occludin proteins decreases." (PMID 39773987, 2025).
intracranial hemorrhage (4 papers, 2018 to 2024). Bleeding within the SKULL, including hemorrhages in the brain and the three membranes of MENINGES. "In intracranial hemorrhage, claudin-5, occludin, and ZO-1 sampled from cerebrospinal fluid may be more specific than serum markers." (PMID 30259344, 2018).
male infertility (4 papers, 2016 to 2023). The inability of the male to effect fertilization of an ovum after a specified period of unprotected intercourse. "Occludin-deficient mice show complex phenotypes, such as gastritis, male infertility, calcification in the brain, thinning of the compact bones, deafness, and lactation failure." (PMID 36806348, 2023). "In this study, we used an interdisciplinary approach to elucidate the underlying mechanism of male infertility in related to OCLN function, including Ocln knockout mice as well as a combined omics analysis and immunofluorescent labelling." (PMID 36518247, 2022). "Mumps virus infecting Sertoli cells reduces occludin and ZO-1 levels, impairs BTB integrity, and disrupts BTB function, leading to male infertility." (PMID 37376572, 2023).
meningitis (4 papers, 2016 to 2024). A disorder characterized by acute inflammation of the meninges of the brain and/or spinal cord. "Several BBB junction molecules were found to be downregulated in meningitis including occludin, claudin-5 and ZO-1, highlighting the BBB breakdown." (PMID 32529267, 2020). "In Neisseria-induced meningitis, MMP-8 was involved in the proteolytic cleavage of the TJ protein Occludin." (PMID 31092253, 2019).
mucositis (4 papers, 2015 to 2025). Mucositis is inflammation and damage of the mucous membranes lining the mouth and other parts of the gastrointestinal (GI) tract. "5-FU-induced mucositis disrupts the intestinal epithelial barrier by altering the expression of tight junction proteins such as ZO-1, occludin, and claudin-1, essential for cell adhesion and permeability regulation." (PMID 40244381, 2025). "Our present studies identified a disruption of the intestinal intercellular structure and a reduced expression of ZO-1, Claudin-7, and Occludin in mice with mucositis." (PMID 34795594, 2021). "Biomarkers were also used to assess the level of intestinal permeability as a result of mucositis; such biomarkers include the tight junction molecules ZO-1, occludin, junctional adhesion molecule-A, and Claudin-2, as well as other biomarkers such as diamine oxidase (DAO) and endotoxin." (PMID 36499758, 2022).
necrotizing enterocolitis (4 papers, 2020 to 2022). Necrotizing enterocolitis (NEC) is a devastating disease that affects mostly the intestine of premature infants. "For example, decreased expression of known tight junction proteins such as ZO-1 and occludin, have been shown to be associated with pathologies such as necrotizing enterocolitis (NEC) and inflammatory bowel disease." (PMID 34690957, 2021). "It was previously reported that the intestinal TJ proteins, namely, ZO-1, Occludin, and Claudin-4, were significantly downregulated in necrotizing enterocolitis (NEC)." (PMID 33426071, 2020). "Furthermore, In a neonatal mouse necrotizing enterocolitis (NEC) model, B. infantis modulates the proper localization of claudin 4 and occludin in TJs, attenuates intestinal permeability, protects intestinal barrier function, and reduces the incidence of NEC." (PMID 35910620, 2022).
non-alcoholic fatty liver disease (4 papers, 2016 to 2023). "Geniposide, in combination with chlorogenic acid, has been reported to display protective effects on gut barrier function by increasing the expression of ZO-1 and occludin to ameliorate non-alcoholic fatty liver disease." (PMID 33919521, 2021). "Furthermore, CBM 588 significantly reduces serum endotoxin levels and hepatic inflammatory indexes and dramatically enhances TJ protein expression (ZO-1 and occludin) in rats with nonalcoholic fatty liver disease." (PMID 34444952, 2021). "In a non-alcoholic fatty liver disease (NAFLD) model, CGA increased the expression of tight junction proteins occludin and ZO-1 in intestinal tissue, decreased the LPS levels, and increased the level of glucagon-like peptide 1 (GLP-1) in the portal vein." (PMID 37444374, 2023).
preeclampsia (4 papers, 2019 to 2023). Preeclampsia is a hypertensive disorder of pregnancy that is characterized by new-onset hypertension with proteinuria presenting after 20 weeks of gestation, and depending on mild or severe forms may initially present with severe headache, visual disturbances, and hyperreflexia. "Previous experiments have shown differences in the distribution of connexins, the expression of VE-cadherin and Occludin and the permeability of endothelial monolayer cells isolated from women with normal pregnancy and preeclampsia patients." (PMID 36620649, 2022). "Similarly, human umbilical vein endothelial cells isolated from pregnant women with preeclampsia showed decreased expression of the junctional proteins cadherin and occludin and increased monolayer permeability." (PMID 34696680, 2021).
prostate carcinoma (4 papers, 2013 to 2022). A carcinoma that arises from epithelial cells of the prostate gland. "The 7 AJ and TJ proteins chosen were E-cadherin, α- and β- catenin, ZO-1, occludin, claudin 1 and claudin 7 and their expression was investigated using an in vitro model of prostate cancer progression." (PMID 24358122, 2013). "Protein levels for occludin were down regulated in the prostate cancer cells CAHPV-10 (−2.8 fold), DU145 (−1.6 fold) and PC-3 (−9.3 fold) but up-regulated in LNCaP (2.4 fold) compared to PNT2." (PMID 24358122, 2013). "Decreased occludin staining in PC-3 HAVcR-1EXP and increased staining in PC-3 HAVcR-1KD suggests that the overexpression of HAVcR-1 would decrease TJ integrity and that targeting HAVcR-1 could, therefore, be a potential therapeutic target for prostate cancer." (PMID 35204839, 2022). "A significant reduction in occludin mRNA levels was observed in CAHPV-10 (−19.08 fold, p = 0.001), DU145 (−3.2 fold, p = 0.003) and PC-3 (−4.3 fold, p = 0.003) prostate cancer cells compared to normal prostate epithelial cells (PNT2)." (PMID 24358122, 2013). "There were no previous descriptions for the fusions NAIP:OCLN, PDE1C:DNAJC6, KANSL1:ARL17B, FOXP2:CREM, and AHSA1:DLG3 in the context of prostate cancer." (PMID 35625354, 2022).